CDK4 (cyclin dependent kinase 4)
Diseases named in the same sentence as CDK4 in open-access papers (continued):
Sharing a sentence is not in itself a finding about the gene and the disease.
leukemia (43 papers, 2011 to 2026). A malignant (clonal) hematologic disorder, involving hematopoietic stem cells and characterized by the presence of primitive or atypical myeloid or lymphoid cells in the bone marrow and the blood. "Palbociclib, a potent and selective inhibitor of CDK4/6, has emerged as a compelling therapeutic intervention for treating leukemia." (PMID 41496019, 2026). "Collectively, these findings uncover a previously unrecognized PSMD14-AKT1/CDK4 regulatory axis in leukemia and position EB as a promising chemical probe and lead compound for the development of targeted covalent inhibitors against oncogenic DUBs." (PMID 41647277, 2026). "CDK4/6 inhibitors induced autophagy in multiple myeloma cells (abemaciclib), fibroblasts, and leukemia cells (palbociclib)." (PMID 40642276, 2025). "Palbociclib is a CDK4/6 inhibitor that has shown promise in the treatment of specific types of leukemia." (PMID 39000261, 2024). "Our present study proved that the expression levels of CDK2, CDK4, Cyclin D1 and Cyclin E were more abundant in the chemo-resistant leukemia cells than in their parental cells." (PMID 37814227, 2023). "Compared with parental sensitive leukemia cells, the protein expression levels of CDK2, CDK4, Cyclin D1 and Cyclin E in chemo-resistant leukemia cells were relatively elevated." (PMID 37814227, 2023). "A notable sub-class of PROTACs showed significantly better degradation of CDK6 over CDK4, suggesting a potential therapeutic use in certain leukemias such as in AML and Ph+ ALL." (PMID 36051751, 2022). "Here, we evaluated the effect of DBF on human leukemia cells in comparison with the established CDK4/6 inhibitor palbociclib, a promising drug candidate for the therapy of leukemia." (PMID 34564151, 2021). "Although the expression of CDK-4 was determined in 463 different analyses, its expression was up-regulated in 53 cancer datasets and downregulated in two cancer studies (leukemia)." (PMID 33732631, 2021). "To identify replication initiation zones with the aim of tracing early DNA replication, we synchronized human GM12878 (primary-like) and K562 (leukemia) cells separately in the G1 phase using the CDK4/6 inhibitor palbociclib." (PMID 34108027, 2021). "Mambalgin-2 was shown to suppress theactivity of these channels and to inhibit leukemia cell proliferation bycausing G1-phase cell cycle arrest and reducing the activity of the cell cycleregulators cyclin D1 and cyclin- dependent kinase CDK4." (PMID 32742733, 2020). "It was shown that both Cylin D1 and CDK4 were reduced in leukemia cells when GPR137 expression was silenced." (PMID 29422775, 2018). "Overexpression of cyclin D1 dependent kinases 4 and 6 (CDK4/6) is a common feature of many human cancers including leukemia." (PMID 28286417, 2017). "In another recent high-profile paper, it was shown that IDH1 mutation in leukemia cells caused MAPK activation, and targeting this pathway through CDK4/6 inhibitor Abemaciclib, more effectively inhibited proliferation in IDH mutant AML than in IDH wild-type AML." (PMID 38086797, 2023). "Spearman correlation analyses between UHRF1 mRNA levels and the gene expression of MYC family members (MYC, MYCN, and MYCL1), as well as CDK4 and CDK6 in the Haferlach and Gu leukemia datasets, indicated positive associations between UHRF1 and c-Myc, CDK4, and CDK6 in ALL." (PMID 36077796, 2022). "Consistent with this, exposure to MWCNT bucky paper was shown previously to reduce the expression of CCND1/CDK4 as well as cell proliferation by triggering cell cycle arrest in G0/G1 phase and increase apoptosis in human leukemia cell lines through modulation of AKT and MAPK signaling pathways." (PMID 26930275, 2016). "In agreement with this hypothesis, several of the genes identified in our analysis have been suggested to be putative therapeutic targets in leukemia, with either preclinical or clinical trials underway (CDK4, CDK6, GSK3b, MYC, LCK, NFkB2, BCL2L1, NOTCH1)." (PMID 21356087, 2011).
leukemia (continued). "Comparing with their parental sensitive leukemia cells, the protein expression levels of CDK2, CDK4, Cyclin E and Cyclin D1 relatively elevated in chemo-resistant leukemia cells." (PMID 37814227, 2023). "Meanwhile, ampelopsin did not result in a significant reduction in the expression of CDK proteins, including CDK4, CDK2, and CDK1, in both leukemia cell lines." (PMID 33924032, 2021). "Remarkably, CDK4 and CDK6 kinases are frequently overexpressed in leukemia and responsible for G1 to S phase cell cycle transition via retinoblastoma protein (RB) dependent activation of an E2F1 transcription factor." (PMID 34564151, 2021). "Some CDKs can be considered oncogenic, e.g., CDK4 in familial melanoma, CDK6 in MLL-rearranged leukemia, and CDK8 in colon cancer." (PMID 25914884, 2015). "Nevertheless, given the poor prognosis and high relapse rate, patients with NUP98r leukemia may benefit from FLT3 inhibitors, BCL2 inhibitors, and CDK4/6 inhibitors, as well as hematopoietic stem cell transplantation." (PMID 40264981, 2025). "The observed effects of the combination on KMT2A-r leukemia cell survival were associated with downregulated expression of genes involved in proliferation and cell cycle progression including MKI67, CCNB1, CENPV, CDK4 and cMYC in infant KMT2A-r leukemia cells PER-485, PER-703 and PER-494." (PMID 35677155, 2022). "In agreement with this view, two studies showed that CDK6 but not CDK4 is required for the proliferation of MLL-rearranged leukemia, despite the fact that both kinases are expressed." (PMID 34573335, 2021). "Flavopiridol is an inhibitor of cyclin-dependent kinases (CDKs) (including CDK1, CDK2, CDK4, CDK5, CDK6, CDK7, CDK8, and CDK9) and has been investigated for the treatment of several types of cancers, including leukemia, liver cancer, and renal cancer, in clinical phase 2 trials (24, –, 26)." (PMID 31822599, 2019). "Also known as alvociclib, this wide spectrum CDK inhibitor targets CDK1, CDK2, CDK4, CDK6, CDK7 and CDK9 and displays antiproliferative efficacy in several solid tumours and sarcomas, as well as in leukaemia, lymphoma and multiple myeloma." (PMID 25625291, 2015). "CDK6, but not its close homolog CDK4, is frequently expressed at high levels in human and murine lymphoma and leukemia and has been proposed to be a driving force for these diseases." (PMID 23948297, 2013). "Targeted inhibitors: Efforts to optimize CDK4/CDK6 blockade (e.g., combination regimens or PROTACs), PI3K/AKT/mTOR inhibition (rapalogues in trials), BH3 mimetics such as venetoclax, and menin inhibitors for KMT2A-rearranged leukemias, several of which have shown promising clinical activity." (PMID 41009342, 2025). "Unsubstituted fascaplysin was early found to affect cell cycle via inhibiting CDK4/6, thus we compared the activity of DBF and other brominated derivatives with known CDK4/6 inhibitor palbociclib, which was earlier shown to be a promising candidate to treat leukemia." (PMID 34564151, 2021). "Furthermore, inhibition of CDK4/6 kinase activity using PD0332991 leads to inhibition of cell cycle progression and accumulation in the Go/G1cell cycle phase in T-ALL primary samples, triggers apoptosis, and blocks progression of leukemia in a mouse model of T-ALL." (PMID 25914884, 2015). "Notably, the combination of ATRA with the CDK4/6 inhibitor (CDK4/6i) palbociclib induces enlarged PML-NB-dependent cytotoxicity through conflicting cell cycle signals, driven by ATRA-dependent activation of mitogenic ERK signaling under conditions of cell cycle arrest in non-APL leukemia." (PMID 40753178, 2025).
lung adenocarcinoma (39 papers, 2013 to 2025). A carcinoma that arises from the lung and is characterized by the presence of malignant glandular epithelial cells. "Our results showing the direct association between expression of cyclin D1, CDK4, and high pRb levels, strongly suggest activation of cyclin D1/CDK4 pathway in lung adenocarcinoma." (PMID 32104498, 2020). "In lung adenocarcinoma and breast cancer, CDK4/6-mediated phosphorylation and activation of USP51 is essential for deubiquitinating and stabilizing ZEB1, thereby promoting cancer metastasis." (PMID 40307228, 2025). "Analysis of The Cancer Genome Altas (TCGA) using the UALCAN database indicated that CDK4 mRNA expression was upregulated in lung adenocarcinoma (LUAD) samples and lung squamous cell carcinoma (LUSC) samples compared with normal samples." (PMID 37833461, 2023). "In vitro, knockdown of RCC1 not only significantly inhibited the proliferation of lung adenocarcinoma cells but also increased the expression levels of p27kip1 and PD‐L1, and decreased the expression level of CDK4 and p‐Rb." (PMID 33630417, 2021). "In the increase in CDK4 copy number that occurred in five lung adenocarcinomas, four of these exhibited an increase in MDM2 copy number." (PMID 32711494, 2020). "In the current study, we report that activation of RB via treatment with the CDK4/6 inhibitor palbociclib in A549 lung adenocarcinoma cells results in a metabolic shift wherein palbociclib alters aspects of glucose and glutamine utilization." (PMID 32624705, 2020). "In addition, anlotinib targets include FGFR/CDK4, among others, and is effective against lung squamous cell carcinoma, lung adenocarcinoma, and small cell lung cancer." (PMID 39648153, 2024). "CDK4 has been shown necessary for tumor progression in a KRAS-induced lung adenocarcinoma model." (PMID 29464099, 2018). "Importantly, the effects of CDK4/6 inhibition in the NSCLC cell lines utilized here were reflected in the genetically-engineered mouse model of Kras-mutant lung adenocarcinoma." (PMID 30167080, 2018). "For another example, the CDK4/6 inhibitor was shown to downregulate p16/cyclin D1/CDK4/(retinoblastoma protein)Rb signaling pathway and enhance the cytotoxicity of PTX for KRAS mutation-positive lung adenocarcinoma cells." (PMID 26900348, 2016). "In lung adenocarcinomas mice, inducing CS by dual inhibition of MEK and CDK4/6, followed by treatment with uPAR-targeting CAR T cells, selectively killed senescent cells and limited tumor growth." (PMID 38972884, 2024). "The mechanism was revealed to inhibit CDK4/CDK6-cyclinD1 complex by increasing p21 expression in colorectal cells, and upregulate p21 expression level in lung adenocarcinoma cells." (PMID 34122110, 2021). "To assess the role of CDK4/6 inhibition on metabolism in NSCLC, we utilized A549 lung adenocarcinoma cells." (PMID 32624705, 2020). "We show that YTHDF1 deficiency inhibits NSCLC cell proliferation and xenograft tumor formation through regulating the translational efficiency of CDK2, CDK4, and cyclin D1, and that YTHDF1 depletion restrains de novo lung adenocarcinomas (ADC) progression." (PMID 31653849, 2019). "In general, downregulation of ZEB1, RECK, TGFBR2 and BMPR2, as well as upregulation of CDK4, CCNE2, EZH2 and DNMT1 has been shown in lung adenocarcinoma and/or squamous cell carcinoma." (PMID 27588394, 2016). "The results indicated that dried apricot polyphenols (DAPs) could cause cell cycle arrest in the G0/G1 and G2/M phases by decreasing the cyclin D1, CDK4, cyclin B1, CDK1, and CDK6 levels in A549 human lung adenocarcinoma cells." (PMID 39796398, 2025).
lung adenocarcinoma (continued). "Recent clinical trials of cyclin-dependent kinase 4/6 inhibitors (CDK4/6i) in human lung adenocarcinoma (LUAD) have not achieved satisfactory results." (PMID 35686110, 2022). "Based on the activity of these CDK inhibitors, we speculated that CDK2, CDK4/6, and CDK5 are candidates that activate DRP1 during the cell cycle in lung adenocarcinoma cell lines." (PMID 33152171, 2021). "Other mechanisms for the combinatorial effects of CDK4/6 and MEK inhibition in the KRAS-driven lung adenocarcinoma model may also be contributing, including an induction of senescence not observed after exposure to palbociclib alone." (PMID 30167080, 2018). "Although CDK4/6 might compensate for CDK2 in regulating cell cycle progression, our data revealed that CDK4/6 is not crucial for mitosis‐related mitochondrial fragmentation in lung adenocarcinoma cell lines." (PMID 33152171, 2021).
lymphoma (34 papers, 2012 to 2025). A malignant (clonal) proliferation of B- lymphocytes or T- lymphocytes which involves the lymph nodes, bone marrow and/or extranodal sites. "Large amounts of Cdk4/cyclin D1 complexes were the main hallmark of these lymphomas." (PMID 27729620, 2017). "While the lymph node specimens did not contain intervening CDK4‐positive cells in the background of lymphoma, the CDK4‐positive cells intervened in the background of lymphoma growth in the thigh tumor, suggesting that the lymphoma cells grew within the WDL." (PMID 39894788, 2025). "The exception appears to be lymphoma lines, which shut off mTOR activity following CDK4/6 inhibition, thus preventing overgrowth and mitochondrial scaling." (PMID 38438376, 2024). "Studies using a genetically modified mouse model of Eμ-myc-induced B-cell lymphoma showed that disruption of the cdk4 locus leads to genomic instability and accelerated lymphoma development via FOXO1." (PMID 36051751, 2022). "eFT226 also caused a G1 cell cycle arrest in lymphoma cell lines due to the inhibition of translation of MYC, CDK4 and cyclin D1, which led to anti-tumor activity in vivo." (PMID 34398253, 2021). "BET-PROTACs have shown synergistic interactions with bcl-2 and CDK4/6 inhibitors in lymphoma probably through the activation of compensatory pathways." (PMID 31470872, 2019). "As CDK6 participates in cell cycle dysregulation in many solid tumors and lymphoma, there is a potential benefit of CDK4/6 inhibitors for the treatment of these tumors; however, de novo or acquired treatment resistance has also been reported in several tumor models." (PMID 35463324, 2022). "This supports the notion that Fbxl8-cyclin D3 axis might be a potential novel biomarker to predict the efficacy of CDK4/6i in lymphomas." (PMID 33122824, 2021). "Disruption of Cdk4 regulation by INK4 while c-myc is overexpressed in B-cells (in a c-myc-3'RR transgenic background prone to develop Burkitt lymphoma (BL)-like lymphomas) leads to the development (in double mutant c-myc-3'RR/Cdk4R24C mice) of lymphoid malignancies closely resembling human MCL." (PMID 22592113, 2012). "We thus established that in both the assessed lymphoma cell lines, the expression levels of CDK1, CDK4, and Cyclin B1 were reduced following treatment with artesunate." (PMID 37719860, 2023). "It has been confirmed that CDK4 and CDK6 are closely related to tumorigenesis, and inhibition of CDK4/6 could bring an anti-tumor effect in several tumors, including lymphoma." (PMID 38589831, 2024). "Virus-positive cells also demonstrated increased sensitivities to Palbociclib compared to virus-negative BJAB cells, which was consistent with previous reports and suggested that CDK4/CDK6 may have additional functions to support the survival and proliferation of virus-transformed lymphoma cells." (PMID 38365882, 2024).
liver cancer (32 papers, 2002 to 2025). An epithelial or non-epithelial malignant neoplasm that arises from the liver. "In this study, our survival analysis and prognostic model screened out the immune gene CDK4 that was significantly associated with the survival and prognosis of liver cancer patients." (PMID 34784846, 2021). "After we found through the database that CDK4 was highly expressed in liver cancer as well as associated with the cancer stage, we subsequently explored it through a series of cell experiments." (PMID 34784846, 2021). "Since CDK4 may be closely associated with the metastasis of liver cancer, future studies should thus mainly focus on the following two points for the corresponding clinical transformation." (PMID 34784846, 2021). "It is important to note that previous reports revealed activation of pathways (such as Akt, TGFβ, and cdk4) in liver cancer that might cause the observed posttranslational modifications of TSPs14,29,32." (PMID 30271949, 2018). "It has been reported that PSMD11 affects liver cancer progression by regulating CDK4 expression and thus affects liver cancer." (PMID 40182048, 2025). "By knocking out lncRNA LOC90784, CDK4 expression is inhibited, thereby inhibiting the proliferation of liver cancer cells, and inducing apoptosis and cell cycle arrest." (PMID 36699068, 2022). "In the TCGA cohort, the GSEA results suggested that high expression of CDK1 and CDK4 was correlated with cell cycle, liver cancer survival, cell cycle checkpoints, DNA replication and cell cycle G2 and M phase transition." (PMID 35193513, 2022). "In general, in patients with liver cancer, the level of CDK4 expression was significantly correlated with advanced clinical-pathological parameters." (PMID 34784846, 2021). "After locking onto the CDK4 gene, we then analyzed the corresponding expression levels of CDK4 from the ualcan.path.uab.edu online website in both normal tissues and liver cancer tissues." (PMID 34784846, 2021). "We noted that the expression level of CDK4 was much higher in liver cancer tissues compared with that of normal tissues at the transcriptome level." (PMID 34784846, 2021). "In liver cancer tissues, the expressions of CDK4 (p = 1E-12) and CDK6 (p = 5.74E-14) were significantly increased." (PMID 34335258, 2021). "First, for patients after liver cancer surgery, whether CDK4 can be used as a tumor marker for related exploration, early warning of liver cancer metastasis, second liver cancer surgery, or early treatment for new metastatic lesions." (PMID 34784846, 2021). "Therefore, the function of CDK4 and its closely related genes in liver cancer is worthy of our further exploration." (PMID 34784846, 2021). "Besides, it has been reported that CDK4 is highly expressed in liver cancer, and more often as a cell cycle regulator in cancer." (PMID 34784846, 2021). "Subsequently, we further confirmed the high expression of CDK4 in liver cancer samples." (PMID 34784846, 2021). "Likewise, our current experimental results show that CDK4 exhibits great potential as a therapeutic target in liver cancer cells, which warrant further exploration and validation." (PMID 34784846, 2021).